MIR1468 (microRNA 1468)
Synonyms: hsa-mir-1468; MIRN1468; mir-1468
Gene: MicroRNA gene on chromosome X (63,786,002 to 63,786,087, reverse strand). Ensembl gene ENSG00000222532.
Diseases named in the same sentence as MIR1468 in open-access papers:
MIR1468 is named in the same sentence as 2 diseases in open-access papers, as found by Europe PMC text mining. Sharing a sentence is not in itself a finding about the gene and the disease. The quoted sentences say what the papers report.
hepatocellular carcinoma (1 paper, 2020). A malignant tumor that arises from hepatocytes. "In fact, MIR1468 was recently shown to promote tumor progression by activating PPAR-γ-mediated Akt signaling in hepatocellular carcinoma." (PMID 32860050, 2020).
MIR1468 also shares sentences with these, for which no sentence is quoted: tumor (1 paper).